C9orf40 (chromosome 9 open reading frame 40)
Synonyms: FLJ10110
Tractability: PROTAC: ubiquitination databases record sites on it.
Gene: Protein-coding gene on chromosome 9 (74,946,583 to 74,952,912, reverse strand). Ensembl gene ENSG00000135045.
Subcellular location (Human Protein Atlas): Cytosol; Nucleoplasm; Centrosome
Genetic constraint (gnomAD): Loss-of-function variants: 2 observed, 4.29 expected, observed/expected ratio (o/e) 0.47, 90% interval 0.19 to 1.42. That is too few expected variants to judge how well the gene tolerates losing a copy. Missense variants: 224 observed, 175.76 expected, observed/expected ratio (o/e) 1.27, 90% interval 1.14 to 1.42. Synonymous variants: 98 observed, 74.33 expected, observed/expected ratio (o/e) 1.32, 90% interval 1.12 to 1.56.
Homologues: Orthologues: chimpanzee C9H9orf40 (99% identical), dog C9orf40 (74% identical), pig C9orf40 (73% identical), rabbit C9orf40 (73% identical), rat C1h9orf40 (53% identical), mouse D030056L22Rik (51% identical).
Diseases named in the same sentence as C9orf40 in open-access papers:
C9orf40 is named in the same sentence as 7 diseases in open-access papers, as found by Europe PMC text mining. Sharing a sentence is not in itself a finding about the gene and the disease. The quoted sentences say what the papers report.
cervical cancer (1 paper, 2017). A primary or metastatic malignant neoplasm involving the cervix. "These genes were also shown to be dysregulated in cancer: C9orf40 was reported to be dysregulated in ovarian carcinoma whereas DNAJC9 was shown to be up-regulated in metastatic cervical cancer in cancer stem cells." (PMID 28056781, 2017).
malignant glioma (1 paper, 2022). A grade III or grade IV glioma arising from the central nervous system. "During the process of illustrating the circadian rhythm pathway, among the 6 coding genes, we exhibited the biological functions of TBPL1, NPAS2, CRY2, and ETNK1; therefore, what are the roles of VPS33B and C9ORF40 in malignant glioma?" (PMID 35194922, 2022). "Fourteen genes within the cellular senescence pathway (AC020907.1, Y_RNA, TMEM72‐AS1, KRT16P2, DLX6‐AS1, AP002414.1, hsa‐miR‐424, TBPL1, NPAS2, CRY2, C9ORF40, AL136115.1, AC102941.1, and AC008738.2) were used to construct a model to evaluate the importance of these genes in malignant glioma." (PMID 35194922, 2022).
metastatic tumors (1 paper, 2023). "In general, overexpression of the C4orf46, C9orf40, C17orf67 and C21orf58 gene of thymoma correlates with tumor immune cell infiltration and gene expression levels of C1orf162, C16orf54 and CXorf21 correlate with immune cell infiltration in many primary and metastatic tumors." (PMID 37373333, 2023).
tumor (2 papers, 2022 to 2023). "After illustrating the circadian rhythm pathway and tumour immune microenvironment pathway, only one coding gene, C9ORF40, and three ncRNAs, AC008738.2, AC102941.1 and AL136115.1, remain to be illustrated." (PMID 35194922, 2022).
C9orf40 also shares sentences with these, for which no sentence is quoted: cancer (1 paper); ovarian carcinoma (1); thymoma (1).